DEFB4B (defensin beta 4B)
Description:
Exhibits antimicrobial activity against Gram-negative bacteria and Gram-positive bacteria, with highest activity against Gram-negative bacteria. Antimicrobial activity against P.aeruginosa seems to be salt-sensitive and is reduced with high salt concentrations greater than 25 mM. Also exhibits antimicrobial activity against the yeast C.albicans. Permeabilizes C.albicans cell membranes via targeting plasma membrane lipid phosphatidylinositol 4,5-bisphosphate (PIP2), thereby leading to cell fragmentation and cell death. Acts as a ligand for C-C chemokine receptor CCR6. Binds to CCR6 and induces chemotactic activity of CCR6-expressing cells, such as immature dendritic cells and memory T cells.
Synonyms: DEFB4P
Gene: Protein-coding gene on chromosome 8 (7,414,855 to 7,416,863, reverse strand). Ensembl gene ENSG00000177257.
Subcellular location: Secreted
Pathways (Reactome):
Immune System: Beta defensins; Defensins
Gene Ontology:
Molecular function: CCR6 chemokine receptor binding; phosphatidylinositol-4,5-bisphosphate binding; protein binding; chemoattractant activity
Biological process: antifungal innate immune response; antimicrobial humoral immune response mediated by antimicrobial peptide; chemotaxis; defense response to bacterium; defense response to fungus; defense response to Gram-negative bacterium; defense response to Gram-positive bacterium; killing of cells of another organism; cell chemotaxis; G protein-coupled receptor signaling pathway; immune response; defense response; positive chemotaxis
Cellular component: extracellular region; Golgi lumen
Homologues: Orthologues: chimpanzee DEFB4A (98% identical), rat Defb3 (50% identical), rat Defb4 (50% identical), mouse Defb4 (45% identical), mouse Defb3 (44% identical). Paralogues in human: DEFB4A (100% identical), DEFB109B (28% identical), DEFB109C (28% identical), DEFB109D (27% identical), DEFB130A (25% identical), DEFB130B (25% identical).
Diseases named in the same sentence as DEFB4B in open-access papers:
DEFB4B is named in the same sentence as 5 diseases in open-access papers, as found by Europe PMC text mining. Sharing a sentence is not in itself a finding about the gene and the disease. The quoted sentences say what the papers report.
psoriasis (2 papers, 2018 to 2023). An autoimmune condition characterized by red, well-delineated plaques with silvery scales that are usually on the extensor surfaces and scalp. "After systemic IL-17A blockade, the expression of those inflammatory mediators (IL36G, S100A8, DEFB4A, and DEFB4B) was decreased in posttreatment psoriasis lesional skin KCs compared to pretreatment psoriasis lesional skin KCs (p < 0.05)." (PMID 37781383, 2023). "The expression of IL-17-driven inflammatory mediators (IL36G, S100A8, DEFB4A, and DEFB4B) in suprabasal keratinocytes was correlated with psoriasis severity and was downregulated by IL-17A blockade." (PMID 37781383, 2023). "After IL-17A blockade, KC expression of IL36G, S100A8, DEFB4A, and DEFB4B in S. corneum and S. granulosum decreased in posttreatment psoriasis lesional skin compared to pretreatment psoriasis lesional skin (p < 0.05)." (PMID 37781383, 2023). "The expression of inflammatory mediators induced by IL-17 in keratinocytes (IL36G, S100A8, DEFB4A, and DEFB4B) was increased in pretreatment psoriasis lesional skin KCs compared to control skin KCs (p < 0.05)." (PMID 37781383, 2023). "Results from qRT-PCR measurements of psoriasis-relevant transcripts showed that levels of DEFB4B, IL36G, LCN2, S100A7, S100A8 mRNA were significantly decreased in rhodomyrtone-treated cultures when compared with cytokine-treated cultures (p<0.0001, all)." (PMID 30321197, 2018). "When we compared KC transcriptome in different epidermal layers, the expression of IL-17-driven inflammatory mediators (IL36G, S100A8, DEFB4A, and DEFB4B) was localized to suprabasal layers (S. corneum, S. granulosum, and S. spinosum) in pretreatment psoriasis lesional skin." (PMID 37781383, 2023).
infection (1 paper, 2024). The state of being infected such as from the introduction of a foreign agent such as serum, vaccine, antigenic substance or organism. "Some of these effectors were responsive to infection stimuli including beta-defensin (BD2, encoded by DEFB4A and DEFB4B) and elafin (encoded by PI3) as they were not present at high concentrations in the uninfected controls." (PMID 39565098, 2024).
DEFB4B also shares sentences with these, for which no sentence is quoted: cancer (1 paper); melanoma (1); skin (1).